SPATA31J1 (SPATA31 subfamily J member 1)
Synonyms: C5orf60
Tractability: Antibody: UniProt predicts a signal peptide or a membrane-spanning region. PROTAC: ubiquitination databases record sites on it.
Gene: Protein-coding gene on chromosome 5 (179,641,544 to 179,658,432, reverse strand). Ensembl gene ENSG00000204661.
Subcellular location: Membrane
Gene Ontology:
Cellular component: membrane
Homologues: Orthologues: macaque SPATA31J1 (77% identical).
Diseases named in the same sentence as SPATA31J1 in open-access papers:
SPATA31J1 is named in the same sentence as 2 diseases in open-access papers, as found by Europe PMC text mining. Sharing a sentence is not in itself a finding about the gene and the disease.
SPATA31J1 shares sentences with these, for which no sentence is quoted: cervical cancer (1 paper); tumor (1).